MYC (MYC proto-oncogene, bHLH transcription factor)
Diseases named in the same sentence as MYC in open-access papers (continued):
Sharing a sentence is not in itself a finding about the gene and the disease.
tumor (continued). "Furthermore, CREPT also recruits RNAPII to the transcriptional region of MYC, which plays a crucial role in the smooth and coordinated transcriptional process that accelerates tumor growth and development and offers a therapeutic strategy targeting their complex in cancer treatment." (PMID 40723282, 2025). "Thus, the oncogenic expression of c-MYC downstream of the mTORC1 pathway could play a role in tumor cell reprogramming to dietary methionine sources through promoting the transcription of MAT2A." (PMID 40299656, 2025). "Additionally, blocking CCL7 and CCR2 with the chemokine inhibitor Bindarit and the CCR2 antagonist INCB3344, respectively, effectively reversed the recruitment of M2‐like macrophages by MYC‐overexpressing tumor cells, suggesting that the recruitment was CCL7‐CCR2 dependent." (PMID 39899538, 2025). "Additionally, MYC activates de novo enhancers and activates oncogenic pathways, such as the WNT pathway, which supports stem cell features and predisposes luminal epithelial cells to tumor initiation." (PMID 38890350, 2024). "As there are multiple FOXO family isoforms and FOXO3 and -4 were also inactivated in the c-MYC tumors, we could not exclude the possibility that other FOXOs compensated for the loss of Foxo1 tumor suppressor in the double-KO studies." (PMID 39325536, 2024). "NHWD-870, a BET inhibitor, could downregulate c-MYC and directly inhibite tumor cell proliferation." (PMID 38566153, 2024). "The MYC gene has a confirmed role in the pathogenesis of MM by intensifying cell proliferation and migration (Notch and Wnt signaling pathways) and stimulating angiogenesis (via VEGF), and its increased activity is associated with tumor progression and occurs in up to 60% of disease cases." (PMID 38473390, 2024). "To further investigate whether targeting tumor cell-intrinsic MYC augmented cisplatin therapy, we crossed Mycflox/flox (Mycf/f) mice with keratin 14-Cre/ERT2 mice (K14CreER) to generate K14CreER; Mycflox/flox mice, in which epithelial Myc can be inducibly deleted by tamoxifen treatment." (PMID 38169606, 2024). "Hence, the local microenvironment has a critical role in MYC-induced tumor formation." (PMID 37450923, 2024). "However, in PBTs the limited presence of tumour-associated antigens (TAAs) due to the low TMB and the increased release of CD47 often detected in MYC-amplified tumours that reduce phagocytosis lead to low levels of antigen presentation and, consequently, lower anti-tumour immunity." (PMID 38732225, 2024). "Deletion of Foxo1 fails to rescue the loss of Rictor’s tumor inhibition effects in c-MYC HCC." (PMID 39325536, 2024). "Considering the tumor suppressing function of FOXO3, rs17069665 and rs4946936 might influence RMS risk and prognosis via regulating the expression of FOXO3 by altering the bindings to MYC, CTCF and/or RELA." (PMID 38720807, 2024). "Due to the dual importance of MYC in normal cell proliferation and its potential to become tumorigenic when overproduced or hyperactive, cells have developed multiple mechanisms to regulate its levels and activity to prevent hyperplasia and subsequent neoplasia." (PMID 39596100, 2024). "Residual tumor cells remaining in patients after treatment and detected in preclinical models are characterized by significant suppression of MYC, and depleting MYC in tumor cells leads to a dormant diapause-like adaptations allowing them to survive under chemotherapy." (PMID 38418814, 2024). "However, MYC expression retrieved from transcriptomic data of HB patients indicated that MYC cannot be used as a predictive marker, as it is nearly unchanged between tumor and normal liver tissue." (PMID 39529166, 2024).
tumor (continued). "Interestingly, miRNA machinery knockdown leads to the activation of proto-oncogenes such as K-RAS and c-MYC, indicating that the expression of tumor-suppressor miRNAs is essential to protect cells from the activation of proto-oncogenes and to maintain cell differentiation." (PMID 38607000, 2024). "As expected, NUDT1 inhibition induced significant cell death in all the tumor cells associated with MYC/MYCN overexpression, whereas those with low MYC/MYCN levels exhibited minimal cell death, underscoring the association between MYC overexpression and NUDT1 dependency." (PMID 38493213, 2024). "Our study revealed the crucial role of the KLF16/MYC regulatory axis in modulating tumor growth and chemotherapy sensitivity in BLCA, suggesting that combining bromodomain inhibitors, such as OTX015 or ABBV-744, with DDP or gemcitabine could be a promising therapeutic intervention for BLCA patients." (PMID 39551759, 2024). "Moreover, HIF-1α cooperates with MYC to shape the tumor immune microenvironment." (PMID 38390324, 2024). "Furthermore, GSVA and GSEA‐HALLMARKER analyses revealed that DCTN2 was positively associated with tumour‐promoting pathways such as the PI3K/AKT/mTOR pathway, MYC_targets, and E2F_targets, indicating that DCTN2 was significantly related to various tumour‐related pathways." (PMID 38842133, 2024). "Should MYC alterations prove common in patients whose tumours progress on treatment RAS(ON) multi-selective inhibition, combined targeting of the RAS and YAP–TAZ–TEAD pathways may provide an avenue of investigation for treating PDAC tumours with such alterations." (PMID 38588697, 2024). "The disappearance of pAKT, the decrease in c-MYC, together with the upregulation of p21 and the decrease in Ki-67, collectively indicate that a potential shift toward reduced proliferation and cell cycle arrest occurred in the tumor following the indicated therapeutic combination." (PMID 38397874, 2024). "Notably, MYC is not only essential for maintaining normal cellular homeostasis where its expression is strictly regulated but its dysregulation appears to be equally important for tumor development and progression." (PMID 39075086, 2024). "Targeting MYC might promote tumor cells to dedifferentiate into other different CSCs." (PMID 38169606, 2024). "Thus, we next investigated whether triptolide would not only reduce MYC levels, but also tumor burden in an orthotopic mouse model of MB." (PMID 38885332, 2024). "A multivariate Cox regression analysis in meta‐OSA indicated that both SQLE mRNA expression and MYC mRNA expression are independent indicators of mortality risk in OSA patients, even when adjusted for clinical factors such as age, MSTS stage and primary tumour site." (PMID 38372422, 2024). "MYC may be additionally involved in other processes relevant to immune-mediated tumor cytotoxicity, including inhibiting ferroptosis and necroptosis, contributing to evasion from anti-tumor immune responses via non-apoptotic mechanisms of programmed cell death." (PMID 39596160, 2024). "We detected ectopic MYC in brat-deficient TICs even prior to tumour growth and show that MYC depletion during this early stage of TIC development mirrors that of HEART1, precluding enhanced rRNA synthesis, cell enlargement and delaying the start of tumour growth." (PMID 38225354, 2024). "The heterogeneity and genomic similarity with human MM create an opportunity for future investigations aimed to longitudinally track the genomic and tumor microenvironment evolution of Vk*MYC MM over time that could inform on key drivers of the progression from SMM to MM human." (PMID 38714690, 2024). "Deregulation of MYC that could occur due to transcriptional overexpression (as in gene amplification, translocation or altered upstream signaling) and/or protein stabilization, leads to high MYC protein levels that consequently drives tumor initiation, progression and maintenance." (PMID 39031286, 2024).
tumor (continued). "MiR-203 is one of the most important tumor suppressor microRNAs involved in the pathogenesis of cSCC (being expressed in high levels in the skin), acting by modulating the expression of the oncogene c-MYC (suppressing its activity) and inhibiting the angiogenesis and cell cycle of tumoral cells." (PMID 37047618, 2023). "Indeed, targeting the transcriptional activity of MYC strongly inhibits tumor growth." (PMID 37400551, 2023). "This generates a catalytically inactive enzyme (dCas9) that is linked either to a strong transcriptional activation domain or to a transcriptional repressor domain, depending on whether a tumor-suppressive MYC target should be activated or an oncogenic MYC target downregulated." (PMID 36969025, 2023). "In addition to miRNAs, several lncRNAs are also involved in the MYC-driven tumor progression." (PMID 37443779, 2023). "Notably, we show that SLC5A6 over-expression alone can induce increased cell growth and a shift toward biosynthesis, whereas conversely, dietary restriction of pantothenic acid leads to a reversal of many MYC-mediated metabolic changes and results in hampered tumor growth." (PMID 37946084, 2023). "In addition, in MYC-overexpressed breast tumour models, metformin combined with anti-apoptotic B-cell lymphoma-2 inhibitors, navitoclax or venetoclax, led to tumour growth inhibition, improved clinical outcomes and tumour infiltration by immune cells." (PMID 37173907, 2023). "Moreover, the high-risk group exhibited a significant enrichment of pathways associated with poor tumor prognosis, including “E2F targets pathway”, “G2M checkpoint pathway”, “MTORC1 signaling pathway”, “MYC targets pathway”, and “RIBOSOME” based on GSEA analysis." (PMID 37629096, 2023). "Additionally, increased metabolic fluxes by MYC may support oscillations tied to cell cycle or other rhythms to become more predominant and better drive tumor cell growth." (PMID 37639465, 2023). "In addition, the crosstalk between MYC and tumor cells and Tregs also deserves attention." (PMID 36966168, 2023). "Importantly, SNHG3/c‐MYC/BMI1 axis may be a novel target for regulating tumor growth and metastasis in BLCa patients." (PMID 36208024, 2023). "Notably, MYC is a well-established regulator of ribosome biogenesis and protein translation, including cap-dependent translation, and can rewire translational control in tumor cells when it is overexpressed." (PMID 37384411, 2023). "Similarly, the tumour suppressor CDKN2A are also categorized c-MYC target genes could control the G1/S transition 47-48." (PMID 37215441, 2023). "Thus, we propose that COA6 is possibly involved in MYC-mediated tumor promotion." (PMID 36982777, 2023). "c-MYC directly promotes CaP development through the upregulated expression of various pro-tumorigenic factors, including ribosome biogenesis, which supports tumor growth and PI3K/AKT/mTOR pathway dysregulation, consequently promoting the survival and growth of CaP cells." (PMID 37895357, 2023). "In addition, we observed a significant activation of numerous tumor-associated biological functions and pathways in cluster A, such as EMT, cell proliferation (MYC targets, G2M checkpoints, E2F targets, and cell cycle), WNT/β-catenin, TGF-β, and PI3K/AKT signaling pathways." (PMID 38170006, 2023). "Thus, it is not surprising that the MYC oncoprotein is closely linked to chemoresistance in different tumor types." (PMID 37755397, 2023). "The significant heterogeneity of luminal, immune, and interstitial cells in PCa LNM may not only directly contribute to tumor progression, but also indirectly result in TME immunosuppression, which may be the cause of metastasis in PCa and in which MYC played an role." (PMID 37221625, 2023).
tumor (continued). "Hence, MYC activation elicits numerous hallmarks required for autonomous tumor growth." (PMID 36959802, 2023). "Importantly, LOH of CTDNEP1 in the tumor may increase the therapeutic window for combined treatment with MYC and CHEK1 inhibition." (PMID 36765089, 2023). "Therefore, we suggest that COA6 may promote the proliferation of LUAD cells by multiple tumor promotion pathways including MYC, PI3K–AKT–mTOR, and ROS." (PMID 36982777, 2023). "Notably, WMhigh cells overall had a significantly higher amount of label incorporation from both glucose and glutamine compared to WMlow cells, even in tightly intermingled tumor regions, arguing for a cell-autonomous effect of increased label uptake due to MYC activity." (PMID 37946084, 2023). "Thus, the loss of CTDNEP1 promoted tumor growth of both MYC-amplified and non-MYC-amplified G3-MB cells in xenografts, suggesting a tumor-suppressive role for CTDNEP1 in G3-MBs." (PMID 36765089, 2023). "In addition, we discovered that highly expressed RPS24 could significantly enrich multiple cancer-promoting signaling pathways, such as the E2F targets, Wnt/β-catenin signaling, G2M checkpoint, and MYC targets, which accelerated tumor cell mitosis." (PMID 36614249, 2023). "Given the strong positive correlation between MYC and YBX1 as well as their corresponding target genes in CD133-high FN RD cells, we decided to focus on characterizing the loss-of-function effects of MYC and YBX1 on RMS tumor growth and stem cell function as well as their potential interactions." (PMID 37345125, 2023). "Besides, we delineated the genomic features of WDHD1 at the pan-cancer level, including expression and mutations, and explored for the first time the relationship between its paclitaxel and rapamycin resistance, tumor heterogeneity, RNA methylation modification, MYC, and E2F pathways." (PMID 37759234, 2023). "Therefore, the over-expression of MGA by the knockdown of P(RR) will curtail the supply of MAX for MYC heterodimerization and stop the MYC-dependent cellular processes from shifting tumor cells from a rapidly dividing state to a more regulated state of division." (PMID 37869088, 2023). "Therefore, c-MYC may be a critical mediator between these carcinogenic signaling pathways and tumor immune response." (PMID 36721232, 2023). "Although we did not detect many sialyl-Lewis related structures by glycomics, which may be due to differences in cell lineage or differentiation, these data suggest that MYC-directed glycosylation may have important implications for tumor cell adhesion beyond immune evasion." (PMID 36897988, 2023). "Our findings, identifying a miR-145-5p/c-MYC/EGFR/MUC1/OCT4 network, provided further evidence demonstrating that the altered activity of non-coding RNAs either as loss of tumor suppressor activity or gain of oncogenic functions might play in the chemoresistance of metastatic lesions." (PMID 37598177, 2023).
tumor (continued). "Thus, the tumor suppressor activity of CTDNEP1 may be exerted in part by inhibiting MYC activity while maintaining cell-cycle homeostasis and genomic stability." (PMID 36765089, 2023). "Hence, MYC amplification is critical for supporting tumor metabolic reprogramming." (PMID 37130865, 2023). "Scientists explored the possible association between the presence of c-MYC, GATA3, and a high level of Ki-67 expression in PTCL patients to confirm whether the GATA3-positive subgroup of tumours is enriched in MYC and proliferative gene signatures compared with other groups." (PMID 35681778, 2022). "Targeting USP1 activity may thus be an alternative therapeutic strategy in MYC-driven tumours." (PMID 36240066, 2022). "However, OGDH is the only mitochondrial enzyme that can convert α-ketoglutarate into succinyl-coA in the TCA cycle and may therefore represent a more promising therapeutic target for MYC-driven tumours." (PMID 35945217, 2022). "Hence, identifying and inhibiting tumor-specific nucleolar regulators (possibly driven by MYC) may lead to the development of novel strategies to block cancer cell growth." (PMID 35159381, 2022). "This showed that MYC targeting genes may be the key to tumor dormancy mechanism." (PMID 35305591, 2022). "Interestingly, targeting MYC has been shown to induce tumor cell immunogenicity." (PMID 35326601, 2022). "Notably, VK*MYC MM cell numbers in the spleen exceeded tumor cell numbers in the BM by far." (PMID 34584204, 2022). "Furthermore, CHCHD4 knockdown significantly reduced MYC expression in xenograft tumours." (PMID 36482116, 2022). "Therefore, we further analyzed the tumor-related pathways and found that SGOL1 expression level was associated with tumor proliferation characteristics, DNA repair, G2M checkpoint, PI3K-AKT-mTOR signaling pathway, DNA replication, cellular response to hypoxia, and MYC target genes." (PMID 36439418, 2022). "MYC seems to be one of the most important carcinogenic factor in human tumorigenesis, and it can act as a transcription factor to promote a wide range of gene expression and play a key role in a variety of tumor processes, including immune escape, invasion, and proliferation." (PMID 34687270, 2022). "Finally, we interrogated a large compendium of 2999 breast cancers to assess whether there was selective pressure to overexpress AK2 in MYC-high tumours." (PMID 35945217, 2022). "However some reports claim that MYC, while promoting primary tumor growth, impairs metastasis, suggesting that MYC inhibition reduces primary tumor growth but could enhance invasiveness." (PMID 36860495, 2022). "In addition to this, the Vk*MYC model allows determination of tumor burden (i.e., levels of circulating M-Spike protein) in the mouse serum using serum protein electrophoresis (SPEP) assay, which is routinely used in the clinic to track MM development and progression." (PMID 35251496, 2022). "Consequently, we deduced that MYC S146L may only be beneficial to tumor cell survival following initial cellular transformation." (PMID 36018850, 2022). "Interestingly we found that CDKN2A,FADD,GATA3,MYC were highly variable between gain and loss in CNV, while at the mRNA expression level these same NRGS were also found to be significantly different in normal tissues compared to tumor tissues." (PMID 35478725, 2022). "Moreover, the tumor cell subpopulations expressing the highest level of PSMB5 (GP3-B1) are different from the ones of MYC, OTX2 or CRX (GP3-B2 for MYC, GP3-C2 for OTX2 and CRX), further supporting the involvement of unidentified SE-associated TFs in regulating PSMB5 transcription in G3-MB." (PMID 36273157, 2022).